IL6 (interleukin 6)
Diseases named in the same sentence as IL6 in open-access papers (continued):
Sharing a sentence is not in itself a finding about the gene and the disease.
infection (continued). "Given that at week 3 post infection, despite an equal content of B-cells, the overall level of il6 expression in the lung is ~10 fold lower in B-IL-6KO mice compared to controls, we may conclude that B-cells serve as a major source of IL-6 in the lung exactly at the early phase of infection." (PMID 35154093, 2022). "Furthermore, DDX5 could inhibit IFN-β and IL-6 production after infection with influenza virus, which suggests that DDX5 may be involved in regulating antiviral innate signaling." (PMID 35583334, 2022). "The higher the levels of IL-1β and IL-6, the more serious the infection may be." (PMID 35531475, 2022). "Interestingly, phiMR003 also suppressed the IL-1β and IL-6 levels induced by KYMR58 infection." (PMID 36123529, 2022). "Besides, IL‐6, an important proinflammatory factor, could activate the immune system and affect the viral load after pathogen infection." (PMID 35478439, 2022). "Indeed, the expression levels of IL‐6 were upregulated in the tissues after N67C infections." (PMID 35635376, 2022). "Moreover, it could be interesting to prospectively evaluate patients by monitoring the recovery of olfactory function and correlating it with IL-6 levels in the early stages of infection." (PMID 33983525, 2022). "Thus, serum AST, DBil, LDH, and IL-6 levels may be potential markers to identify patients with severe or critical infections in the early stage." (PMID 36052305, 2022). "In addition, infections with T3SS and T6SS mutants were associated with two distinct host response profiles and transcription factor activation patterns including AP1, STAT1 and SP1, and lower levels of IL-6 and IL-8 secretion." (PMID 35508983, 2022). "Thus, immediately after infection, pro-inflammatory cytokines, such as IL-6 and IL-17, produced by the resident immune cells, upregulate key chemokines and adhesion molecules to recruit more leukocytes, which in turn are regulated by anti-inflammatory cytokines and regulatory T-cells." (PMID 36051240, 2022). "Additionally, immunosuppressive agents may increase the risk of infection and block the production of several inflammatory markers (serum CRP, IL‐6, etc.), which could impair accurate diagnosis of PJI." (PMID 36181336, 2022). "However, TNF-α expression was detected in Delta infection, albeit later and milder than the previous variants, indicating that its regulation is independent from that of CCL4 and IL-6." (PMID 36073824, 2022). "Furthermore, ATF3 positively regulated inflammatory cytokines IL-6 and IL-12p40 might be able to contribute to the infection resolution." (PMID 35370996, 2022). "Even if exacerbated inflammatory response in case of infection may lead to detrimental consequences, this has notably been exemplified earlier with IL-6 and development of arthritic pathologies, antiviral response remains essential to counteract most of virus-induced pathogenesis processes." (PMID 35887383, 2022). "An excessive release of inflammatory factors, including IL-6, IL-12, IL-1β, and TNF-α, from immune disorders caused severe apoptotic damage to immune organs, which was consistent with MG-Rlow infection-induced damage to the spleen, thymus, and bursa of fasciola." (PMID 36139393, 2022). "Notably, the Mavs–/–Il6–/– DKO mice were almost completely resistant to the lethal N67C infections." (PMID 35635376, 2022). "As hypoglycaemia is known to induce inflammation, including IL‐6 expression, and decrease immune responsiveness, it is not surprising that it may also exacerbate biologic predisposition to infection." (PMID 35644866, 2022). "Guan found that IL-6 and IL-10 were closely related to bloodstream infection and suggested that IL-10 might distinguish G- and G+ infection, but the diagnostic effect of IL-10 was not ideal, with a sensitivity of 64.1%." (PMID 35432366, 2022). "Therefore, we also examined the secretion of IL‐6 and IL‐8 in the full skin models after infection." (PMID 35212482, 2022).
infection (continued). "In a recent study, LuzScheffer and Latini showed that regular PE with light / moderate intensity causes an anti-inflammatory response by stimulating the production of IL-6 and neopterin that subtly reduce the risk of infection and chronic non-communicable diseases and generate neuroprotection." (PMID 35204231, 2022). "Indeed, IL-6 has been associated with severe clinical forms of human pneumovirus (hRSV), pandemic H1N1 influenza virus, or H5N1 influenza A virus infections." (PMID 35062301, 2022). "Production of nitrite among control, infection and empty vectors are found to be similar but when a designed synthetic circuit is induced in infected cells, nitrite production is increased which shows that the IL6 synthetic biological circuit is shifting macrophage polarization towards M1 phenotype." (PMID 35011356, 2021). "Conversely, the infection-adjusted associations of non-specific indicators of severe HI insult with proinflammatory cytokines, IL-6 and IL-8, may suggest a systemic inflammatory response, which becomes stronger after TH is completed." (PMID 34795631, 2021). "IL-1β and IL-6 are key drivers of Th17 cell responses and can promote functional plasticity towards the more pro-inflammatory ex-Th17 cell fate, where Th17 lineage cells produce IFN-γ, which is associated with protection against certain infections but also with immune-mediated pathology." (PMID 34489958, 2021). "Interestingly, the inhibition of TNF-α and interleukin-6 prevented infection-induced cell death." (PMID 34829902, 2021). "Furthermore, let-7 family miRNAs could directly modulate the expression of key immunoregulatory cytokines including il-6 and il-10, which hinted the downregulation of these miRNAs could increase the levels of these cytokines upon infection." (PMID 34222406, 2021). "The therapeutic effect of MPX was evaluated in a murine model, revealing that MPX could protect against lethal infection with E. coli in mice and reduce the expression of the inflammatory factors IL-2, IL-6, and TNF-α, thereby alleviating intestinal inflammation." (PMID 34177825, 2021). "IL-6 is a key cytokine that triggers increased liver production of acute-phase proteins (APPs), such as C-reactive protein (CRP) and fibrinogen, causing hypercoagulable disease, which is characterized by thrombotic and embolic phenomena and can predict the severity of infection." (PMID 33946649, 2021). "IL-6 is secreted by several cells of the immune system but is mainly produced by macrophage and T cells activated by a viral or bacterial infection or by other immune cells representing a signal for the induction of a response to the infection by cells of the immune system." (PMID 33981314, 2021). "Therefore, serum baboon and pig IL-6 and SAA may serve as useful biomarkers for inflammation and pig kidney graft failure associated with rejection or infection, and might allow improved monitoring and management of primates with pig organ grafts." (PMID 34956220, 2021). "Measurement of serum creatinine, SAA, and pro-inflammatory cytokines (serum baboon and pig IL-6 and IL-1β) in baboon recipients may prove useful in indicating whether a baboon recipient is developing rejection or infection, though it might be insufficient to distinguish conclusively between the two." (PMID 34956220, 2021). "Upon infection, cardiac-resident cells, such as cardiomyocytes, endothelial cells, and fibroblasts, may contribute to acute inflammation by secreting cytokines such as IL-1β, IL-6, TNF-α, and IL-18." (PMID 34504807, 2021). "Furthermore, DDX5 could significantly inhibit IFN-β and IL-6 production after infection with RNA virus." (PMID 33909701, 2021). "Finally, we found that while infection with non-treated PAO1 did not affect the expression of two key inflammatory cytokines, TNFα and IL-6, infection with zinc-exposed PAO1 significantly increased the expression of both TNFα (2-fold, p < 0.01) and IL-6 (3-fold, p < 0.01)." (PMID 34948118, 2021).
infection (continued). "Hence, IL-6 has been defined as the emblematic cytokine for this severe infection." (PMID 33550983, 2021). "Moreover, BS26 induced higher levels of IL-6 than P1/7 did at 12 h post-infection." (PMID 34357984, 2021). "However, S. parasuis BS26 induced higher levels of IL-6 at 12 h post-infection." (PMID 34357984, 2021). "On the other hand, F. nucleatum subsequential infection maintained the secretion levels of IL-1β, IL-6 and TNF-α in pulmonary epithelial cells compared to the single P. aeruginosa group, which may be due to the low cellular viability caused by P. aeruginosa pretreatment." (PMID 33816348, 2021). "Moreover, EBN restores the immune system in the context of infection by influencing viruses through regulation of pro-inflammatory cytokines, such as IL-6 and TNF-α, and cytokines with regulatory properties, such as IL-10 and CCL2, which are also involved in the progression of UC." (PMID 33967768, 2021). "SARS-CoV-2 possesses a large spectrum of virulence, varying from asymptomatic infection to severe acute respiratory syndrome (SARS) and multi-organ failure linked to cytokine storm, with possible Kawasaki-like syndromes and auto-immune manifestations, linked to interleukin 6 (IL-6) hypersecretion." (PMID 34376184, 2021). "An explanation for this association could be that the up-regulation of angiotensin-converting enzyme 2 receptor (ACE2R) after infection may lead to the production of cytokines such as IL-1, IL-10, and IL-6, and the regulation of B cell activation is triggered to respond." (PMID 34430148, 2021). "Correlating with these data, higher TNF-α and IL-6 production was observed in vitro by LPS or Pam3CSK4-stimulation of equal numbers of total cells from the bone marrow and the spleen, or equal volumes of blood, from mice 7 or 14 days after the primary infection compared to uninfected mice." (PMID 34975887, 2021). "We then assessed the transcriptional profiles of pro-inflammatory cytokines Interleukin-6 (IL-6) and interleukin-15 (IL-15) and anti-inflammatory interleukin-10 (IL-10) under normal or iron-depleted conditions and determined how these were affected by infection." (PMID 34571900, 2021). "The biological functions mediated by IL-6 are very complicated, which mainly include: 1) After the organism is stimulated by tissue injury, infection and inflammation, IL-6 could induce the production of cytokines including acute phase reaction proteins via NF-κB." (PMID 34504432, 2021). "Remarkably, when levels of both these analytes were expressed as a sMIL ratio (sMAdCAM/IL-6), we observed a clear delineation of in-patient and convalescent data into discrete categories based on disease progression, gender, time from infection, and intriguingly serological status." (PMID 34194420, 2021). "Thus, IL-17 might promote pulmonary inflammation, following the infection by neutrophil and monocyte migration to the lungs, and by activating other cytokine cascades (G-CSF, TNFα, IL-1β and IL-6)." (PMID 34205262, 2021). "In these patients, simultaneous infection with several viral genotypes may induce a more vigorous local immune response compared to patients infected by a single viral genotype, consistent with the increase in IL-6 expression level in the ECCs." (PMID 33750983, 2021). "IL-6 levels in the first 24 hours after trauma are correlated with trauma severity (first hit), whereas its levels during the 48-72 hour period following trauma can be attributed to secondary effects such as infections, surgery, transfusions, and pre-traumatic conditions." (PMID 35126355, 2021).
infection (continued). "Therefore, we can only speculate that the sustained reduction in IL-6 production may be related to an as yet undiscovered mechanism of immune tolerance that leaves an indelible fingerprint of past infection in bone marrow myeloid progenitors." (PMID 34399830, 2021). "IL-6, a cytokine significantly elevated in DENV-infected AG129 mice and associated with disease in humans is an activator of STAT3 and thus this is a pathway unique in the mouse that may induce FB during DENV-infection." (PMID 33410734, 2021). "However, the effect of IL-6 could be different depending on the TMEV strains because SJL mice receiving IL-6 prior to TMEV DA infection are free from the disease." (PMID 34067536, 2021). "In addition, we chose IL-6 and adrenaline as targets in a pharmacological approach to further validate the roles of these factors in mediating the mortality of neonatal mice subjected to EV-A71 infection." (PMID 31857694, 2020). "Interestingly, IL-6−/− mice were not protected by a live vaccine from subsequent challenge with virulent B. dermatitidis, but unvaccinated IL-6-deficient mice were not more susceptible to primary infection." (PMID 32545735, 2020). "However, we cannot infer from the lack of change in IL-6 levels that TMAO does not operate by regulating proinflammatory molecules, since the regulatory effects of IL-6 in inflammation and infection is complicated, and many other pro- and anti-inflammatory cytokines were not measured in this study." (PMID 32060329, 2020). "In contrast, after aerosol infection with Mtb, IL-6-/- mice exhibit only an initial increase in bacterial burdens accompanied by a delayed IFNγ induction; however, these mice are eventually able to contain mycobacterial growth and to mount a protective memory response to secondary infection." (PMID 33334075, 2020). "Therefore, the presence of infection was only associated with a slight increase of the early pro-inflammatory response (higher IL-6 at T2), but did not change the global picture of the immune response." (PMID 32377009, 2020). "Similarly, available reports often restrict secondary infections to documented blood stream infections, which may significantly underestimate the infectious complications of anti-IL-6 therapy in the critically ill." (PMID 33195334, 2020). "Notably, the mRNA levels of Tnf, Il6, Il1b, Cxcl10, and Cxcl5 were significantly increased and that of Il10 decreased in lung tissue from Ppara-/- mice, compared with Ppara+/+ mice, during Mabc infection." (PMID 32155958, 2020). "Indeed, infections and related inflammatory processes, by up-regulating IL-6, induce hepcidin synthesis, which, in turn, blocks Fpn-mediated iron efflux from the cells to blood, thus reducing serum iron concentration and increasing iron overload in reticuloendothelial cells." (PMID 32664543, 2020). "Additionally, we established the importance of IL-6 for inflammatory cell recruitment to the site of the infection, since IL-6 KO infected mice showed a reduced number of macrophages, dendritic cells, and neutrophils in spleens compared to wild-type infected mice." (PMID 33322581, 2020). "On day 98 post infection, the relative amount of Foxp3+ Treg was slightly decreased whereas during the earlier progression of infection comparable frequencies of these cells could be detected in wild type and IL-6−/− mice." (PMID 33375150, 2020). "Therefore, it may be possible that IL-6 exerts a more significant influence on the development of a TH17 immune response during a high-dose infection with the lab-adapted Mtb strain H37rv." (PMID 33375150, 2020). "Thus, in this study, we further analyzed IL6 mRNA expression of the Chinese soft-shelled turtle under acute cold stress and/or bacterial challenge in the spleen and intestine, which are import for turtles fighting infection." (PMID 32466093, 2020). "Additionally, IL-6 KO mice showed reduced splenomegaly at 1 week post-infection." (PMID 33322581, 2020).
infection (continued). "Indeed, IL-6 measurements evidenced a worthy association with days of hospital stay days, ICU admission, and mortality rates with affordable value for personalised clinical practice and infection management." (PMID 33273888, 2020). "Indeed, this short-lived elevation appears important in candidalysin-triggered responses, since reduced availability of ATP (via Apyrase) significantly inhibits EGFR activation, MAPK signalling (c-Fos, MKP1) and IL-6 release following infection or toxin treatment." (PMID 32178483, 2020). "This would indicate that IL-6 dysregulation could be important in a subset of patients that is not linked to viral load or stage of infection, but likely associated with differences in individual host response to the virus." (PMID 33298930, 2020). "Additionally, IL-6 KO mice exhibited reduced splenomegaly during the early phase of the infection." (PMID 33322581, 2020). "Remarkably, CSF2 (encoding granulocyte-macrophage colony-stimulating factor), IL-6 (interleukin-6), IL-12B (interleukin-12 subunit beta), CSF3 (granulocyte colony-stimulating factor), and TNF (tumor necrosis factor) were extremely highly expressed upon infection with WT V. vulnificus (log2 FC > 8)." (PMID 32817457, 2020). "Also, the identity of oral mucosal monocytes or macrophages that express active IL-1β/IL-6 during an infection is unknown and warrants future studies." (PMID 33240286, 2020). "Furthermore, infection by hRSV seems to reach CNS, which produces high levels of IL-6 in the zone." (PMID 30936869, 2019). "Elevated IL6 levels in the mother may occur as part of a pro-inflammatory response to infection." (PMID 30795743, 2019). "CRP and leptin but not IL-6 were significantly higher in the Ob group regardless of any underlying health condition, the progress of pregnancy, or the presence of any complication or infection." (PMID 30909605, 2019). "In IL6, neither allelic nor genotypic analysis showed any association with infection." (PMID 32219005, 2019). "Importantly, however, IL-6 acts as a pyrogen in the presence of infection or inflammation." (PMID 31022834, 2019). "In response to infection or neuronal tissue damage, microglia rapidly alter their morphology and increase phagocytic activity, initiating an innate immune response by secreting various inflammatory molecules, including interleukin (IL-6) and tumor necrosis factor-α (TNFα)." (PMID 31165723, 2019). "The raised levels level of IL-6 in stunted children after six months of intervention might be due to the improvement in cell-mediated immune response toward the infection/inflammation stimuli, because of essential micro and macronutrients rich food supplementation." (PMID 31394828, 2019). "Interestingly, levels of F. prausnitzii are inversely correlated with inflammatory markers such as IL-6 in low-grade inflammatory disease, indicating that this beneficial bacterium may play an inhibitory role in local intestinal inflammation and infection." (PMID 32038590, 2019). "While we did detect small increases in the levels of CXCL10 and IL-6 with abortive infection of VA1 in SW-1088 cells, it is unclear whether these increases are biologically significant, and further characterization may reveal host responses that are significantly induced by abortive infection." (PMID 31289185, 2019). "At day 6 post-infection, 25-OH-cholecalciferol treated mice displayed lower numbers of colonic innate and adaptive immune cell populations as compared to placebo controls that were accompanied by lower intestinal concentrations of pro-inflammatory mediators including IL-6, MCP1, and IFN-γ." (PMID 31552040, 2019). "Interestingly, in our work, most of the studied cytokines were found to be higher in those animals receiving any treatment in comparison to the control group, with the exception of IL-6, a biomarker related to the severity of the infection, which was accordingly reduced in the treated animals." (PMID 31484389, 2019).